RNU7-73P (RNA, U7 small nuclear 73 pseudogene)
Synonyms: U7.73
Gene: Small nuclear RNA gene on chromosome 3 (37,573,151 to 37,573,213, reverse strand). Ensembl gene ENSG00000239105.
Homologues: Orthologues: chimpanzee U7 (98% identical), macaque U7 (97% identical), rat LOC120093318 (70% identical). Paralogues in human: RNU7-19P (89% identical), RNU7-20P (86% identical), RNU7-35P (86% identical), RNU7-70P (86% identical), RNU7-12P (84% identical), RNU7-143P (84% identical), RNU7-152P (84% identical), RNU7-37P (84% identical), RNU7-66P (84% identical), RNU7-7P (84% identical), U7 (84% identical), RNU7-125P (83% identical), and 142 more.